Y_RNA (Y RNA )
Gene: Miscellaneous RNA gene on chromosome 19 (36,858,227 to 36,858,329, reverse strand). Ensembl gene ENSG00000206669.
Homologues: Orthologues: chimpanzee Y_RNA (100% identical), macaque Y_RNA (96% identical). Paralogues in human: Y_RNA (92% identical), RNY3 (89% identical), Y_RNA (89% identical), Y_RNA (88% identical), RNY3P14 (87% identical), Y_RNA (87% identical), RNY3P1 (86% identical), Y_RNA (86% identical), Y_RNA (85% identical), RNY3P16 (84% identical), RNY3P4 (84% identical), RNY3P9 (84% identical), and 95 more.